IL6 (interleukin 6)
Diseases named in the same sentence as IL6 in open-access papers (continued):
Sharing a sentence is not in itself a finding about the gene and the disease.
Stroke (continued). "In stroke patients, CSF IL-6 predicted stroke size while serum IL-6 did not." (PMID 35898322, 2022). "High IL-6 levels showed to be a negative prognostic marker for the 90-day mortality after stroke." (PMID 36145501, 2022). "Moreover, MEDS-23 significantly decreased prostaglandin E2 levels in the hypothalamus and hippocampus of post-stroke rats, but did not prominently alter the levels of interleukin-6 and tumor necrosis factor-α." (PMID 35053779, 2021). "Pre-clinical studies show that selected serum biomarkers including C-reactive protein (CRP), interleukin-6 (IL-6), tumor necrosis factor-alpha (TNFα), matrix metallopeptidases (MMP), and vascular endothelial growth factors (VEGFs) may play a role in BBBP post-stroke." (PMID 34744972, 2021). "A 2017 meta-analysis on IL-6 (4 studies, 419 patients) could only confirm significantly higher levels in CE-stroke patients compared to lacunar strokes but not to non-CE strokes combined." (PMID 33716927, 2021). "Colchicine could thus constitute a new and important treatment for secondary prevention after stroke, by targeting inflammation via pleiotropic actions, including the inhibition of interleukin-1β (IL1-β) and IL-6 synthesis, and the reduction of microtubule-dependent leucocyte motility and mitosis." (PMID 34300276, 2021). "Furthermore, mice receiving young microbiome possessed much higher levels of IL-4 and granulocyte-colony stimulating factor (G-CSF), while the elevation of levels of IL-6, tumor necrosis factor alpha (TNF-α), Eotaxin, and CCL5 were shown in the mice with aged microbiota after stroke." (PMID 33439913, 2021). "Furthermore, there are premises suggesting value of some biomarkers in the diagnosis of specific stroke types, such as cardioembolic stroke (vWF, TNFα), hemorrhagic stroke (GFAP, MMP-9), large- and small-artery disease (IL-6; TNFα), or lacunar stroke (Glu, GABA)." (PMID 31701356, 2020). "Experimental stroke studies which incorporate social isolation or social defeat stress have shown that both tissue and functional stroke outcome is affected by the increased expression of TNF-α and IL-6, increased glucocorticoid production, and suppression of the protooncogene bcl-2." (PMID 32477259, 2020). "However, the addition of IL-6 to a validated, clinical-based stroke prognostic model did not improve the prediction of poor outcome." (PMID 31906994, 2020). "As IL-6 levels were investigated in the acute phase (<8 h) post-stroke in the present study and IL-6 is known to peak after 24 h, this suggests that IL-6 is not a reliable biomarker in the acute phase after stroke debut." (PMID 32595585, 2020). "Astrocytic IL-6 was critical to the role of hyperforin in promoting the infiltration of T-helper (Th) type 2 cells to the ischemic hemisphere and Th2-derived cytokine IL-4, relative to Th1 and Th1-derived cytokine interferon-γ (IFN-γ), which decreased during stroke recovery." (PMID 31133816, 2019). "Furthermore, we confirmed that the proinflammatory cytokines IFN-γ, TNF-α, and IL-6 were elevated in plasma even 12 months after MCAO compared with those in the sham-12 m group, indicating that chronic systemic inflammation persists after stroke onset." (PMID 31316450, 2019). "Experiments performed by the Lee group showed decreases in the expression of pro‐inflammatory cytokines TNF‐α, IL‐6, IL‐1β, cell adhesion molecules ICAM‐1 and VCAM‐1, and chemokines MCP‐1 and MIP‐1α after intraparenchymal transplantation of fetal‐ and iPSC‐NSCs in a rodent stroke model." (PMID 30747485, 2019). "In order to explore the roles of astrocytes in post-stroke inflammation, the levels of inflammatory factors were detected in primary astrocytes at 0 h, 6 h, 12 h, 24 h, and 48 h after 6-h OGD, including TNF-α, IL-6, IL-10, inducible nitric oxide synthase (iNOS), IL-1β, and CXCL10." (PMID 31426811, 2019).
Stroke (continued). "In addition, the secondary mediators of ischemic cell death and blood-brain barrier disruption, such as IL-6, IL-1β, MMP-3 and iNOS, may constitute useful biomarkers of CKD-induced stroke severity." (PMID 31015533, 2019). "However, a meta-analysis of 24 studies indicated that the translation of IL-6 into clinical practice for prognosis of poor outcome after stroke was unlikely to be of benefit." (PMID 31269910, 2019). "In addition, the phagocytic behavior of alveolar macrophages obtained from naïve animals was reduced, whereas gene expression of TNF-α and IL-6 in these cells was increased, after exposure to serum from Stroke (but not Sham) rats." (PMID 30290827, 2018). "In stroke models, adult progenitor cell therapy leads to decreased tissue levels of pro-inflammatory cytokines such as interleukin-1 alpha (IL1α), interleukin-1 beta (IL1β), and TNF-α and interleukin-6 (IL-6) and increased levels of anti-inflammatory cytokine such as IL-10." (PMID 29548333, 2018). "Additionally, macrophages and endothelial cells, but not epithelial cells, from Stroke animals exhibited increased IL-6 gene expression." (PMID 30290827, 2018). "Moreover, IL-6 gene expression was increased both in macrophages and endothelial cells, but not in epithelial cells, isolated from the lungs of Stroke animals." (PMID 30290827, 2018). "Inflammation, which could drive the progress of cardiovascular diseases, could also be regulated by vitamin D. Vitamin D could inhibit the production of inflammation factors, such as interleukin 6 (IL-6) and tumor necrosis factor alpha (TNF-α), and as a result affect the progress of stroke." (PMID 29495586, 2018). "Similarly, it would explain the finding that rtPA failed to decrease stroke-induced increases of IL-6 and CCL2 protein levels in ischemic ColXV KO mice." (PMID 28079884, 2017). "In the same vein, JAK3 inhibition with 10 mg/kg decernotinib did not affect stroke-induced upregulation of Ccl2, Cxcl10, and Cxcl1, chemokines important for immune cell trafficking, nor proinflammatory mediators IL-1β, IL-6, Tnfα, Ptgs2, and Mmp-9 that exacerbate stroke damage." (PMID 28790974, 2017). "Furthermore, we showed that steppogenin suppressed inducible NF-kB activation and the subsequent induction of proinflammatory mediators, such as NO, PGE2, IL-1β, IL-6, TNF-α, IL-12 and that it blocked the neuronal disorders including Alzheimer’s disease, Parkinson’s disease, and stroke." (PMID 29207498, 2017). "The serum levels of TNF-α, CRP, TGF-β, IL-4, IL-6, IL-10, IL-17, and IL-23 were all increased on days 1, 3, and 7 after stroke when compared with levels in the control group (all p < 0.05); however, the content of IFN-γ was lower in stroke patients than in controls at each time point (p < 0.01)." (PMID 27682880, 2017). "However, in a study of adults with stroke and no signs and symptoms of concomitant infection, IL-6 showed a significant inverse correlation with final neurological impairment and infarct size." (PMID 28253907, 2017). "In summary, our data here suggest that post-stroke EE improves stroke outcomes in an apparently pro-angiogenesis manner through astrocytic HMGB1-mediated inhibition of PSD and PSA, and also through astrocytic HMGB1-induced production and secretion of IL-6 from activated astrocytes." (PMID 28845299, 2017). "However, only IL-6 and IL-10 were positively correlated with NIHSS on day 3 after stroke." (PMID 27682880, 2017). "Although initial systemic inflammation, characterized by circulating IL-6 and IFN-γ production, may peak within 6 h following stroke, it has become increasingly evident that systemic immune suppression takes place as a compensatory mechanism against brain damage." (PMID 26742037, 2016). "Importantly, IL1A, ILAB, IL6 and TNF and other anti-stroke target genes were up-regulated in males." (PMID 27672514, 2016).
Stroke (continued). "National Institute of Health Stroke Scale (NIHSS); hemorheological detection; coagulation function; and serum inflammatory markers, tumor necrosis factor-alpha (TNF-α), interleukin-1β (IL-1β), and interleukin-6 (IL-6), were used to investigate the effects before and 14 days after the treatment." (PMID 26074992, 2015). "However, the expression of IL-6 was not statistically different among the sham, stroke control, and apelin-13 treatment groups (data not shown)." (PMID 26391329, 2015). "Similarly, high levels of IL-6 are raised in the brain tissue or cerebrospinal fluid (CSF) in AD, AIDS dementia complex, multiple sclerosis, stroke, PD and traumatic brain injuries and IL-6 receptors are expressed on neurons at synapses and can regulate neurotransmitter release." (PMID 24952384, 2014). "A prospective cohort study and systemic review revealed that plasma levels of IL-6 were associated with poor outcome after both ischemic and hemorrhagic strokes; however, it was not clear whether IL-6 increased before or after stroke onset." (PMID 23431245, 2013). "However, since levels of dimethylarginines peak when IL-6 has already significantly decreased during the first day after stroke, ADMA and SDMA are unlikely to induce the hyperacute increase of IL-6 in the first hours after stroke." (PMID 23158556, 2012). "However, as with IL-6, TNF-α has also demonstrated neuroprotective effects in cerebral injury and could be related to the different stages of stroke pathogenesis." (PMID 22132330, 2011). "We tested whether interleukin (IL)-6, C-reactive protein (CRP), and fibrinogen more strongly associate with fatal compared to nonfatal myocardial infarction (MI) and stroke." (PMID 19554082, 2009). "However, it is of note that IL-6 did not withstand correction for stroke severity in this study." (PMID 37794467, 2023). "Our analysis revealed that the indirect effect of post‐stroke proinflammatory cytokine IL‐6 on functional disability through stroke recurrence is less than 20%, which means that over 80% of functional damage results from the pathway of IL‐6 to functional disability without stroke recurrence." (PMID 37287421, 2023). "A hypothesis put forward by the authors refers to the fact that the increased risk of these vascular events could be related to the controversial role attributed to IL-6 in stroke, whose high levels have a negative effect on the volume of the cerebral infarct in the long term." (PMID 37754054, 2023). "Our findings have been confirmed by other researchers who believe that IL-6 and TNF-α may be the key inflammatory markers in stroke patients, showing a significant increase in serum levels in numerous studies, within a few hours after the onset of ischemia up to the 90th day after stroke." (PMID 36142524, 2022). "In the multivariate model, such correlation of YKL-40 with recurrent stroke persisted in these two stroke subtypes (adjusted HR 1.46; 95% CI 1.03–2.06; P = 0.03 and HR, 1.89; 95% CI 1.12–3.18; P = 0.02, respectively), while no statistical significance received for IL-6." (PMID 35761288, 2022). "Moreover, the expression of RGM-A rather than other inflammatory indicators, such as CRP and IL-6, continued decreasing 8 to 14 days after stroke, indicating that SIDS might last longer than the inflammatory response." (PMID 36188375, 2022). "Furthermore, for a more advanced model, which may even evaluate the severity and risk factor of the ICAS without the need to image based data, Interleukin-6 and Lipoprotein-associated phospholipase A2 would allow the model a deeper understanding of ICAS and the causes of stroke." (PMID 39979931, 2025). "We used the measured values of iFABP, IL-6, and TNF-α in both PSD and non-PSD stroke patients to construct an OPLS model and evaluate the relationship between the expression levels of these biomarkers and group classification." (PMID 38084247, 2023).
Stroke (continued). "Stroke patients with metabolic syndrome had increased plasma levels of the proinflammatory cytokines CRP, IL-6 and TNF-α but decreased levels of the anti-inflammatory cytokine IL-10 compared to stroke patients without metabolic syndrome and nonstroke patients." (PMID 37587512, 2023). "Stroke increased the expression of inflammatory genes, including pro-inflammatory IBA1, IL-6, CD86, and anti-inflammatory CD206 (infarcted vs. non- infarcted, one-way ANOVA)." (PMID 36812289, 2023). "T cells lacking Bim have a reduced production of several pro- (e.g. IL-6, IFN-γ) and anti- (e.g. IL-4, IL-10) inflammatory cytokines, which have been shown to play critical roles in stroke injury." (PMID 35149957, 2022). "We confirmed that brain IL-6, IL-1β, TNF-α, CCR2, and MCP-1 expression levels were not significantly different between ND/veh and DD/STZ mice prior to stroke (data not shown)." (PMID 35784349, 2022). "The multiple linear regression analysis was used to analyze age, gender, BMI, mRS, CAT, SOD, hydrogen peroxide, MDA, TNF-α, and IL-6 for factor independently correlated with HGS in non-paretic and paretic limbs of stroke patients." (PMID 33126675, 2020). "Exposure to BALF from Stroke or Sham animals did not change alveolar macrophage behavior, or gene expression of TNF-α and IL-6." (PMID 30290827, 2018). "IL‐6, but not TNF‐α, measured at baseline has been considered to be an independent predictor of worsening in the first 24 hr after stroke (Muir, Weir, Alwan, Squire, & Lees, 1999)." (PMID 29484258, 2018). "Compared to stroke, OGV a.s. significantly reduced the pro-inflammatory marker IL-6 by 49%, but had no influence on IL-10 levels." (PMID 27902774, 2016). "Our data show that levels of the pro- and anti-inflammatory markers IL-6, CRP and IL-10 differ as early as at 6 h after stroke onset between patients with and without post-stroke infection." (PMID 25613713, 2015). "In subjects with CEI subtype and metabolic syndrome, PWV was more significantly and positively related to vWF but not with TNF-α, CRP, IL-6, IL-1β and PAI-1 compared to subjects without metabolic syndrome and the same subtype of stroke." (PMID 24571954, 2014). "Stroke induced an increase in MCP-1 at 6 h and 72 h after ischemia in the diabetic peritoneal cells, while IL-6, CCR2, and CD36 gene expressions were not different between the normal and diabetic cells." (PMID 24886035, 2014). "While computational models have explored isolated aspects of post-stroke inflammation, such as TNF-α-mediated microglial activation or IL-6’s dual neurotoxic/neuroprotective roles, no study has yet integrated TNF-α, IL-6, and IL-10 into a unified mathematical model." (PMID 41557608, 2026). "Furthermore, with the exception of the CRP level (P < 0.05), the other inflammatory predictors (IL-6 level, NLR, WBC count, and NEUT%) did not change significantly within 24 h after stroke (P > 0.05)." (PMID 36188375, 2022). "Considering the continuous increase in stroke morbidity/mortality and the lack of non-invasive biomarkers of the disease, our study aimed to evaluate TNF-α, IL-6, and IL-10 levels in the non-stimulated (NWS) and stimulated (SWS) whole saliva of stroke patients." (PMID 34433866, 2021). "In the past, there have been many attempts to treat stroke by intervention on the peripheral immune system, mainly through the intervention of cytokine receptors, such as TNF-α, IL-1, IL-6 and IL-10, while most of the attempts failed to be translated into clinical application." (PMID 34876161, 2021). "In our study, we reported higher serum levels of IL-6 and TNF-α and higher percentage of peripheral CD4+ cells and CD4+CD28 null in subjects with acute ischemic stroke in comparison with subjects without stroke." (PMID 30995924, 2019).
Stroke (continued). "Our study clearly revealed that KO mice exhibited extremely elevation of TNF-α, IL-1β, and IL-6, suggesting that the absence of IRAK-M can exacerbate the brain tissue injury of stroke through releasing larger amounts of proinflammatory cytokines in the acute phase of stroke." (PMID 30622459, 2018). "Among subjects with lacunar subtype and metabolic syndrome, PWV (after correction for age and gender) was more significantly and positively related to CRP, IL-1β, IL-6, TNF-α, vWF and PAI-1 compared to subjects without metabolic syndrome and the same subtype of stroke." (PMID 24571954, 2014). "IL-6 is induced by tumour necrosis factor α and IL-1β, and then leads to the releases of CRP, fibrinogen, and cell adhesion molecules, though the cellular origin of IL-6 after stroke is not clear." (PMID 19901973, 2009). "Moreover, there were significant negative correlations between ovarian IL-6 and ovarian IL-10 expression and 2d ART performance, suggesting that ovarian cytokine expression may directly affect stroke outcomes." (PMID 37408003, 2023). "Although no significant changes in pro-inflammatory cytokine (IL-1β, IL-6, TNF-α) and chemokine (MCP-1, MIP-2α) gene expression were observed at 6 h, 24 h and 72 h after the 50 min ischemic occlusion, IL-1β, IL-6 and MIP-2α expression tended to increase 6 h after stroke." (PMID 30842652, 2019). "Up-regulated serum and brain pro-inflammatory cytokines elicited by TBI or stroke were attenuated by treatment with rhEPO, although EPO administration enhanced BDNF up-regulation elicited by cerebral ischemia, but did not prevent inflammatory gene up-regulation (e.g., IL-1β, IL-6, TNF-α)." (PMID 23675319, 2013).